CCNB2 (cyclin B2)
Diseases named in the same sentence as CCNB2 in open-access papers (continued):
Sharing a sentence is not in itself a finding about the gene and the disease.
tumor (continued). "The boxplots showed that the expression levels of CCNB1, CCNB2, and CHEK1 were significantly higher in primary tumor than those in the normal liver for LIHC patients from TCGA (p<0.001)." (PMID 30228980, 2018). "The present analysis showed, for the first time, that the anti-tumor effect of fisetin was mediated mainly through activation of CDKN1A, SEMA3E, GADD45B and GADD45A and down-regulation of TOP2A, KIF20A, CCNB2 and CCNB1 genes." (PMID 28052097, 2017). "In the pathway in cell cycle, we found that the expression of Ccna2, Cdc25a, Mcm3, Mcm6, Ccnb2, Mcm5, Cdk1, Gadd45a were down-regulated in the MMQ tumor stem-like cells." (PMID 28163656, 2017). "Bcl2, VEGFA, PTEN, Jun, Fos, APC2 were up-regulated and Ccna2, Cdc25a, Mcm3, Mcm6, Ccnb2, Mcm5, Cdk1, Gadd45a, Myc were down-regulated in MMQ tumor stem-like cells group." (PMID 28163656, 2017). "In pathway in cancer and cell cycle, Bcl2, VEGFA, PTEN, Jun, Fos, APC2 were up-regulated and Ccna2, Cdc25a, Mcm3, Mcm6, Ccnb2, Mcm5, Cdk1, Gadd45a, Myc were down-regulated in the MMQ tumor stem-like cells." (PMID 28163656, 2017). "Unsupervised hierarchical cluster based on relative quantification of the 5 E2F-induced genes, CCNA2, CCNB1, CCNB2, MSH6 and MCM7, by RT–qPCR divided the 24 tumours into two groups." (PMID 22045185, 2011). "Moreover, the protein levels of PLK‐1, CCNB1, CCNB2, and SIRT2 were observed to decrease in a dose‐dependent manner in tumor tissues following treatment with VS‐5584 in comparison to the control group." (PMID 37658623, 2023). "Furthermore, by performing IHC staining using mouse tumor tissues, we found that SR9009 treatment reduced the expression of FOXM1 and its target genes CCNB1, CCNB2 and Survivin." (PMID 36357378, 2022). "Huh-7 cells with CCNB2 knockdown and Huh-7 cells without CCNB2 knockdown were injected subcutaneously into the experimental group (KD group) and the control group (NC group), respectively, to observe tumour formation." (PMID 35349480, 2022). "The expression levels of MAD2L1 and CCNB2 are potential indicators of TME status changes in RMS, which may help guide the prognosis of patients with RMS and the clinical staging of tumours." (PMID 34838000, 2021). "The tumor markers CDKN2A and KRT7 were the most upregulated genes with fold changes 10.7 and 4.8, respectively, while markers for proliferation (MELK, CDK1, MKI67, CCNB2, BUB1, FOXM1, CDKN3) had fold changes spanning from 2.0–2.7." (PMID 35008799, 2021). "Based on this inference, we screened three key miRNAs (hsa-miR-10b-3p, hsa-miR-23b-3p, and hsa-miR-139-3p) targeting four hub mRNAs (CCNB2, KIF18B, PLK1, and TOP2A) using the correlation analysis, survival analysis, expression analyses in stage, distant metastasis, tumor, and normal tissues." (PMID 33869028, 2021). "Cyclin B2 (CCNB2) was further investigated since it appeared near the top of the list of differentially expressed genes in the presence of high B-Myb level, and transgenic mice expressing high levels of Cyclin B2 level are prone to tumor development." (PMID 33747961, 2021). "In addition, CCNE1, CCNE2, CCNB2, CCNA2, and CDK1 genes were highly expressed in fetal tumor tissues." (PMID 34395530, 2021). "Up-regulation of CCNB2 and CDK1 accelerates tumor cell mitotic progression." (PMID 34944787, 2021). "Next, we identified candidate herbs and their effective components that may have an inhibitory impact on tumor progression via three hub genes (TOP2A, NUF2, and CCNB2)." (PMID 33946043, 2021). "Therefore, we further studied the role of CCNB2 on secreting of SASP cytokines and cell senescence mediated tumor aggressiveness." (PMID 34512164, 2021).
tumor (continued). "Interestingly, TCGA data analysis revealed that the CDK1, CDK2, CCNB2, and SKP2 genes were significantly upregulated, but the SKP1 gene was downregulated in tumor samples compared with normal samples." (PMID 31717435, 2019). "The expression of CCNB2, KIF4A, and TPX2 were upregulated in the advanced tumor stages." (PMID 30254986, 2018). "MP-HX downregulated the expression of genes that could promote anti-apoptotic effect, cell cycle progression, tumor development and progression, which include BIRC5, CCNA2, CCNB1, CCNB2, CCNE2, CDK1/2/6, GINS2, HELLS, MCM2/10 PLK1, RRM2 and SKP2." (PMID 30042885, 2018). "Among them, CCNB2, KIF4A, and TPX2 were further upregulated in advanced tumor stage." (PMID 30254986, 2018). "Using a combined geneset of these 5 remaining cell cycle-related genes (BUB1B, CCNB1, CCNB2, TTK and CDK1) as well as ADAM7 and FAM72B, we also observed a statistically-significant reduction in disease-free survival of patients with tumours exhibiting alterations in gene expression (p = 0.015)." (PMID 25519703, 2014). "UBE2C, CCNB1, CCNB2, PLOD2, NUP210, MELK, CDC20 were overexpressed in tumours and in CIN3/CIS relative to both Normal and CIN1/CIN2, suggesting that they could have an important role to play in the early phase of tumorigenesis." (PMID 21338529, 2011). "UBE2C, CCNB1, CCNB2, PLOD2, NUP210, MELK, CDC20 genes were overexpressed in tumours and in CIN3/CIS relative to both Normal and CIN1/CIN2, suggesting that they could have a role to play in the early phase of tumorigenesis." (PMID 21338529, 2011). "The interaction network showed that FOXM1 was closely correlated with those proteins who are involved in the cell cycle, such as cyclin-dependent kinase 1 (CDK1), CDK2, Cyclin B1 (CCNB1), as well as CCNB2, indicating FOXM1 may act as an important regulator of the tumor cell cycle." (PMID 37159818, 2023). "Furthermore, TPX2, ZWINT, UBE2C, CCNB2, CDK1, BUB1, and BIRC5 may orchestrate the stemness, proliferation, and invasion of tumor cells." (PMID 34671679, 2021). "The present analysis showed, for the first time, that the anti-tumor effect of fisetin was mediated mainly through modulation of multiple signaling pathways and via activation of CDKN1A, SEMA3E, GADD45B and GADD45A and down-regulation of TOP2A, KIF20A, CCNB2 and CCNB1 genes." (PMID 28052097, 2017). "Il6 deficiency also reduced hepatic mRNA levels of Stat3 target genes (Birc5, Bcl2l1 and Ccnd1), cyclins (Ccna2, Ccnb1, Ccnb2), and markers of proliferation (Mki67) and HCC (Afp) in livers from FGF19-expressing mice, further demonstrating the role of IL-6 in mediating FGF19-driven tumour growth." (PMID 28508871, 2017). "Regarding CCNB2 and CDK1, a recent study with primary HCC tissue samples showed that the downregulation of CCNB2 and CDK1 led to the inhibition of cell proliferation and cell cycle shutdown in the G2/M phase, indicating that the overexpression of CCNB2/CDK1 may promote tumour cell proliferation." (PMID 31754223, 2019). "The vast majority of genes were equally expressed in tumor and non-tumoral, control pituitary glands, including CCNL1, CCNE2, CCNB2, CCNA1, CDK18, CDK19 and CDK20." (PMID 35260162, 2022). "Further gene co-expression network analysis and prognostic analysis indicated CDK1, CCNB2, and CDC25A as the hub tumor-promoting genes in LUAD but not in LUSC, which were further validated in other datasets." (PMID 34446056, 2021). "We investigated the expression of ASPM, CCNB2, CDCA5, KIAA0101, PRC1, and UBE2T in 12 LUAD tumor tissues and their adjacent non-malignant lung tissues." (PMID 33937050, 2021). "There is no staining of TTK, CCNB1, and CCNB2 in normal human lung tissues; however TTK, CCNB1, and CCNB2 showed strong positive in NSCLC tissues; the majority of positive cells were tumor cells and immune cells." (PMID 32969465, 2020).
tumor (continued). "The relative expressions of CCNB1, CCNB2, and CHEK1 mRNA were 3.938±3.887-, 3.225±3.388-, and 3.186±3.508-fold upregulated in 20 tumor tissues versus adjacent nontumor tissues, respectively." (PMID 30228980, 2018). "RT-PCR analysis of the transcriptional expression of cell cycle genes showed a significantly increased expression of ccnA1, ccnB2, ccnD3, ccnE1, cdc25b, and E2F1 and a significantly decreased expression of ccnD2 in the Fhit-transfected versus non-transfected tumor cells." (PMID 32545680, 2020).
cancer (90 papers, 2007 to 2026). A tumor composed of atypical neoplastic, often pleomorphic cells that invade other tissues. "Cyclin B2 (CCNB2) is a subtype of B-type cyclin that is associated with the prognosis of several cancers." (PMID 38300330, 2024). "Ccnb2 (Cyclin B2) is a cell cycle related gene, which is associated with cancer progression and prognosis." (PMID 36733828, 2022). "In our research RMI2 interacts with cell division cycle-associated protein 3 (CDCA3) and cyclin B2 (CCNB2), which are also related with malignant tumors." (PMID 33083148, 2020). "In addition to this, CCNB2 transgenic mice are highly susceptible to tumorigenesis and CCNB2 is often overexpressed in human cancers." (PMID 38300330, 2024). "In cancer, CCNB2 is often overexpressed, contributing to uncontrolled cell proliferation and tumorigenesis." (PMID 40564876, 2025). "Although the influence of CCNB2 on cancer progression is well-documented, its potential involvement in PCa remains unexplored and warrants further investigation." (PMID 41049007, 2025). "Defects in CCNB2 led to the failure of the G2/M checkpoint during the cell cycle, which in turn brought on gene alterations and the development of cancer." (PMID 39911278, 2025). "Although the role of CCNB2 in the progression of many cancers is widely investigated, little is known about the effect of CCNB2 on ccRCC." (PMID 38300330, 2024). "Our results, supporting increased proliferation of CM and EPDC progenitors, agree with the reported increased proliferation and altered CC progression in Lmna −/− MEF and increased CCNB2 expression in cancer cell lines with LMNA knockdown." (PMID 39273049, 2024). "It has also been reported that serum circulating CCNB2 mRNA level in cancer patients is significantly higher than that in the normal population and benign diseases." (PMID 35037540, 2022). "The results of CCNB2 and expression in various cancers showed that compared with the normal tissues, the expression of CCNB2 increased in BLCA, BRCA, OV, GBM, UCEC and many other cancers, but only decreased in LAML." (PMID 34908101, 2022). "The differential expression of CCNB2 in cancer and normal tissues is detected across a variety of cancers, a finding that was observed in both databases." (PMID 34908101, 2022). "According to evidence, HMGA2 promotes and accelerates cancer cell proliferation through Cyclin A, Cyclin E, Cyclin D1, Cyclin B2." (PMID 35488374, 2022). "In our study, we used GEPIA2 and TIMER databases to examine the expression of CCNB2 in different cancers." (PMID 34908101, 2022). "Except for CCNB2, multiple cyclins were involved in the regulation of cancer progression and development." (PMID 34354775, 2021). "Accumulating studies revealed that CCNB1, CCNB2 and TOP2A are associated with the prognosis of cancer and active carcinoma pathogenesis 38-40." (PMID 32201520, 2020). "Another study found that the circulating CCNB2 mRNA level in serum was significantly correlated with cancer stage and metastasis status." (PMID 28427189, 2017). "The “Hallmark apoptosis”, a common feature of cancers, was enriched with APC/C-mediated degradation of cell cycle protein, Cyclin B2 mediated events and PLK1 signaling events, highlighting their roles in the development of cancers." (PMID 27991568, 2016). "Serum circulating CCNB2 mRNA levels were found to be higher in lung and digestive tract cancer patients compared to normal controls and were correlated with cancer stage and metastasis status." (PMID 23282137, 2013). "CCNB2 (7.4-fold) another cyclin overexpressed in several cancers, was interestingly proposed as a serum marker for various cancers as serum CCNB2 mRNA was significantly elevated in patients versus benign diseases or normal." (PMID 22905093, 2012).
cancer (continued). "Ccnb2 is a member of the Cyclin family and a carcinogenic gene for various cancers." (PMID 40565262, 2025). "In LUAD, CCNB2 could promote proliferation, migration, invasion, and cell cycle G0/G1 phase transition of cancer cells." (PMID 34446056, 2021). "The role of CCNB2 in cancer progression and metastasis has also been widely revealed." (PMID 34354775, 2021). "Since there are wide effects of CCNB2 on the progression of multiple types of cancers, we therefore speculate that CCNB2 has a potential regulatory role in the progression of TNBC." (PMID 34354775, 2021). "Validation with systems biology using reweighted 20 types of cancer signature genes revealed that CCNB2 isthe only common target in BC and its related PBMCs, which was further validated by qRT-PCR implying a significantincrease in the level of CCNB2in the BC patients." (PMID 34455715, 2021). "CCNB1 and CCNB2 were overexpressed in multiple human cancers." (PMID 34497666, 2021). "Previous data showed that the radiosensitivity of cancers could be regulated by circRNAs, such as circ_0086720, circRNA versican, and circRNA Cyclin B2." (PMID 33882945, 2021). "CCNB2 is synthesized at G1 phase in cancer cells and downregulated at anaphase." (PMID 34354775, 2021). "Cyclin B2 (CCNB2) is a member of the cyclin family that is overexpressed in many types of cancers." (PMID 34298705, 2021). "Recently, studies have suggested that CCNB2 expression is increased in a variety of human cancers." (PMID 33937050, 2021). "CCNB1, CCNB2, and CCNA2 are the authorizing members of the cyclin family, critical for regulation of cellular growth, proliferation, and apoptosis; and consequently, associated with cancer development and progression." (PMID 32752229, 2020). "CCNB2 is a cell cycle protein, which is highly expressed in cancer tissues." (PMID 31275405, 2019). "The top 1 network in the spleens of A.SW mice was categorized as “Cell Cycle,” “Reproductive System Development and Function,” and “Cancer,” including down-regulated genes: cyclin family (Ccne1, Ccnb1, and Ccnb2) and cell division cycle family (Cdc20, Cdc25b, and Cdc25c)." (PMID 30941144, 2019). "Since several publications revealed that altered CCNB2 expression is seen in many cancer types, therefore further investigation to elucidate the mechanism by which CCNB2 exerts its effects may prove useful in the development of novel anticancer agents." (PMID 23282137, 2013). "Oncogenes such as MYC, AKT1, AKT2, cyclins CCNA2, CCNB1, CCNB2, CCNE1, CCNE2 and cyclin-dependent kinases CDK1 and CDK4, which were upregulated under androgen treatment, exhibited a significantly reduced expression following PVT1 knockdown, thereby modulating cancer-associated oncogenic pathways." (PMID 41792045, 2026). "These discoveries suggest that targeting CCNB2 could represent a new approach to treating cancer." (PMID 41049007, 2025). "By analyzing the clinical significance and prognosis of G2/M related genes (PLK1, CDK1, CCNB1, and CCNB2) in various cancer tissues, we found that they were up-regulated in most cancer types, and their down-regulation showed better overall survival rates in cancer patients." (PMID 37007025, 2023). "Notably, CCNB2 has been reported for the abnormal expression in multiple types of cancers." (PMID 34354775, 2021). "Similarly, CCNB2 is also a key regulator of the cell cycle and may play a role in the development and progression of cancers in humans." (PMID 33187219, 2020). "Cyclin B2 (CCNB2), a key regulator of the cell cycle, has been reported to be upregulated in human cancers." (PMID 40626556, 2025). "Therefore, CCNB2 may become a promising target for humans in the fight against cancer." (PMID 38300330, 2024). "SCL/TAL1 interrupting locus (STIL) promotes proliferation, invasion, and cancer progression by regulating the expression of CDK1, CCNB2, CDC20, CCNA2, BUB1, and AURKB." (PMID 36661515, 2023).
cancer (continued). "Cyclin B2 (CCNB2), a member of the cyclin family, mainly plays a role in G2/M transformation and is up-regulated in human cancer." (PMID 34908101, 2022). "Among all cyclin genes analyzed, CCNA2, CCNE2, CCNB2, CCNB1, CCNF, and CCNE1 were most elevated in the included cancers." (PMID 33996604, 2021). "The upregulated of cyclin B1, cyclin B2, and CDK4 indicated the radiation treatment stimulates the subpopulation of cancer-stem-like cells cell cycle progression and proliferation." (PMID 33931075, 2021). "In this subtype, FOXM1, TOP2A, CCNB1, CCNB2, and CDC25A participate in DNA repair and are activated during disease relapse or play a role in the prognosis of other cancers, thereby supporting the poor prognostic characteristics of the DP.BCG+ subtype." (PMID 33535616, 2021). "Meanwhile, CDK1, CCNA2, CCNB2, BUB1B and CDC20 were classified as cancer-related genes, and RRM2 was an FDA approved drug target." (PMID 33083112, 2020). "Besides the cell division-associated genes like CCNB2 and BUB1B, we also found genes such as TPX2, BIRC5, TOP2A, SPAG5 and HMGB1, were among the top 10 highly expressed genes in the cell subset, which were reported to be directly or indirectly associated with cancer invasion." (PMID 31888172, 2019). "Activation of CCNB2 and ASPM genes induces tumorigenic phenotypes in a number of cancers, whereas their inhibition abrogates cellular proliferation in mice and induces genomic instability." (PMID 23282137, 2013). "Moreover, single-cell RNA sequencing analysis revealed that CCNB2, XRCC2, and CENPI are enriched in cancer cells within BC tissues." (PMID 40202151, 2025). "Using Timer 2.0, we found that PLK1, CDK1, CCNB1, and CCNB2 were upregulated in different cancer types compared with normal samples from the TCGA data set." (PMID 37007025, 2023). "Meanwhile, CCNB1, CCNB2, and CDK1 are highly expressed in almost all cancer types, which may play an important role in cancer." (PMID 34337056, 2021). "The recognized cancer genes CCNB1 and CCNB2 were also identified as WT-related genes." (PMID 33765954, 2021). "The gene expression levels of cyclin B1 (CCNB1), cyclin B2 (CCNB2), Aurora A (AURKA), Aurora B (AURKB), and PLK-1 (PLK1) were increased from stages 1 to 4; however, the genes for D-type cyclins were expressed in a stable manner across the cancer stages." (PMID 30235818, 2018). "Furthermore, AREG affected downstream molecules like BIRC5, CCNA2, CCNB2, TOP2A, MMP9, MMP1, CXCR4, have roles in development and progression of various types of cancers." (PMID 30517191, 2018). "Importantly, we detected increased mRNA half-lives for cancer-related transcripts such as CCNA2, CCNB2 and CDKN1A that were previously shown to be stabilized by ELAVL1." (PMID 24417896, 2014). "We found that four genes are highly expressed in HCC, among which four genes, CCNB1, CNB2, CDK1, and CYP3A4, are highly expressed in tumors, while CCNB1, CCNB2, and CDK1 are highly expressed in almost all cancer types, which may be involved in the important tumorigenesis or progression." (PMID 34337056, 2021). "CCNB2 and BUB1 might be involved in the cancer stem cells to promote LUSC progression." (PMID 32411535, 2020). "Thus, although CCNB1 and CCNB2 have been previously reported to act as therapeutic target genes in HCC, the clinical significance of CCNB1 and CCNB2 needs to be investigated in cancer-related research." (PMID 31886163, 2019).